CTSD (cathepsin D)
Diseases named in the same sentence as CTSD in open-access papers (continued):
Sharing a sentence is not in itself a finding about the gene and the disease.
metabolic disease (3 papers, 2019 to 2023). A congenital disorder (due to inherited enzyme abnormality) or acquired (due to failure of a metabolically important organ) disorder resulting from an abnormal metabolic process. "Differential expression of AGT and CTSD in Homc cells between OA samples and normal samples might indicate that the development and metabolic disorder of chondrocytes are involved in the progress of OA23,which is consistent with our results." (PMID 37853066, 2023).
adenocarcinoma (2 papers, 2021 to 2023). A common cancer characterized by the presence of malignant glandular cells. "CTSD was significantly expressed in AdCC than in polymorphous low-grade adenocarcinoma (PLGA)." (PMID 37198626, 2023).
infectious disease (2 papers, 2010 to 2022). A disorder directly resulting from the presence and activity of a microbial, viral, or parasitic agent in humans. "CTSD (cathepsin D), CD44 (CD44 antigen), and COL1A2 (collagen alpha-2) were associated with the pathways of “infectious disease: viral” and “immune system”." (PMID 36704102, 2022). "The comparison of the level of CTSD transcript showed a 2 fold increase between healthy young probands and acutely aged patients with infectious diseases." (PMID 20716329, 2010).
neurological disease (2 papers, 2023 to 2024). "Although there is an intimate connection between Cathepsin D and autophagy, this has been mostly reported in the neurological disease conditions." (PMID 36701399, 2023).
autosomal recessive disease (1 paper, 2018). Autosomal recessive form of disease. "Out of the 3 heterozygous variants for potential autosomal recessive diseases in the offspring we found the CTSD and FTCD variants eligible for prenatal testing." (PMID 29373990, 2018).
cardiac diseases (1 paper, 2025). "It has been reported that cathepsin D, as one of the lysosomal proteins is reduced in human heart diseases." (PMID 40149863, 2025). "Due to cathepsin D’s protective function in cardiac remodeling, exogenous supplementation or induction of expression of cathepsin D may be beneficial for the relief of cardiac diseases." (PMID 40149863, 2025).
intestinal disorder (1 paper, 2026). A non-neoplastic or neoplastic disorder that affects the small or large intestine. "Collectively, our findings reveal a novel miR-214-3p/CTSD axis that regulates lysosomal homeostasis during neonatal intestinal maturation, providing a potential therapeutic target for porcine intestinal disorders." (PMID 42117833, 2026).
myopathy (1 paper, 2017). A disease of the muscle in which the muscle fibers do not function properly. "Cathepsin D mediates early stages of perichondral ossification, and although myopathy was reported in zebrafish morphants no cartilage phenotypes were noted." (PMID 28715414, 2017).
psychiatric disorder (1 paper, 2020). A disorder characterized by behavioral and/or psychological abnormalities, often accompanied by physical symptoms. "In a similar manner to CTSD-deficient mice, knockdown of DCTN5 in a murine model of psychiatric disorder susceptibility genes also results in abnormal mania-related hyperactivity." (PMID 32325768, 2020).
CTSD also shares sentences with these, for which no sentence is quoted: cardiovascular disease (5 papers); Parkinson’s (5); acute myocardial infarction (3); amyotrophic lateral sclerosis (3); kidney disease (3); multiple sclerosis (3); postpartum cardiomyopathy (3); autism (2); bacteremia (2); cervical cancer (2); CLN10 disease (2); endometrial cancer (2); Farber disease (2); inflammation (2); metastatic melanoma (2); pterygium (2); retinopathies (2); Salla disease (2); Shock (2); sphingolipidoses (2); acute coronary syndrome (1); acute lymphoblastic leukemia (1); adenomyosis (1); airway hyperresponsiveness (1); anal carcinoma (1); astrocytomas (1); atopic dermatitis (1); benign breast diseases (1); benign breast tumours (1); benign tumours (1).
A further 79 diseases each share a sentence with CTSD in 1 paper.